MMP14 (matrix metallopeptidase 14)
Diseases named in the same sentence as MMP14 in open-access papers (continued):
Sharing a sentence is not in itself a finding about the gene and the disease.
cancer (continued). "To further test this relationship, we examined the expression of MMP-14 in human cancer cell lines with differential regorafenib sensitivity." (PMID 39199626, 2024). "believe that TUG1 accelerates cancer EMT by regulating the miR-26a-5p/MMP14/p38 MAPK/Hsp27 axis in vitro and in vivo." (PMID 39026978, 2024). "This would be in line with studies indicating that the MMP14-generated sBSG fragment, released by cancer cells, acts to induce MMP2 activity in neighboring fibroblasts." (PMID 38892056, 2024). "The co-culture of ASCs with cancer cells leads to increased expression of MMPs, such as MMP-2, MMP-9, and MMP-14, in both ASCs and cancer cells." (PMID 39519109, 2024). "Computational chemistry techniques have been used to design and synthesize MMP-14 inhibitors for cancer treatment." (PMID 37513440, 2023). "(b) Phase contrast images show the growth of cancer cell colonies with the indicated manipulations of MMP14 and CTNNA1 after 8 days surrounded by matrix." (PMID 36892272, 2023). "Remarkably, MMP14 (MT1-MMP) has a very important role in cancer cell invasion and metastasis due to its regulatory role in invadopodia functions and its ability to degrade ECM molecules and basically collagen." (PMID 36342580, 2023). "MMP14 is concentrated on the surface of cancer cell invadopodia and destroys a number of VSMC components: collagen types I, II, and III; fibronectin; tenascin; and perlecan." (PMID 38003931, 2023). "Studies in animals have demonstrated that MMP-14 plays an important role in the spread of cancer cells to other parts of the body." (PMID 37513440, 2023). "Accordingly, in endothelial cells, Prox1 negatively regulates the metalloprotease MMP14, which is involved in cancer invasion and angiogenesis." (PMID 37508533, 2023). "Membrane-type MMP-14, also known as MT1-MMP, is involved in the progression of various types of cancer and is an activator of MMP-2." (PMID 38003553, 2023). "(c) Images show the effect of modulating matrix proteolysis via either MMP14 Crispr KO or MMP14 over-expression in cancer cells (green) both organotypic and spheroid assays including fibroblasts (magenta)." (PMID 36892272, 2023). "(d) Images show the effect of combinatorial modulation of matrix proteolysis and cancer cell-cell adhesion via Crispr KO of CTNNA1 and/or MMP14 and/or MMP14 over-expression in cancer cells (green) in both spheroid assays including fibroblasts (magenta)." (PMID 36892272, 2023). "MMP-14 is an enzyme expressed on the cell membrane that promotes cancer metastasis and angiogenesis." (PMID 36741760, 2023). "MMPs (MMP-2, MMP-9, MMP-14) are able to damage the capillary layer and at the same time promote the exosmosis of cancer cells." (PMID 37895400, 2023). "(b) Images show the effect of combinatorial modulation of matrix proteolysis and cancer cell-cell adhesion via Crispr KO of CTNNA1 and/or MMP14 and/or MMP14 over-expression in cancer cells (green) in both organotypic assays including fibroblasts (magenta)." (PMID 36892272, 2023). "Matrix metalloproteinase-14 (MMP-14) regulates cancer migrationand metastasis by directing extracellular matrix remodeling and cellmotility." (PMID 39473938, 2023). "MMP-14 has a central role among the MMPs and acts in cancer metastasis by degrading the ECM, increasing the secretion of pro-MMP2, pro-MMP9 and pro-MMP13, while cleaving membrane-anchored growth factors and cytokines." (PMID 36656313, 2023). "Recent reviews have also suggested that MMP-14 can be used as an indicator of a patient’s prognosis for cancer." (PMID 37513440, 2023). "For example, MMP14 was reported to be up-regulated in some types of cancer and to promote cancer cell invasion." (PMID 36199581, 2022). "Knockdown approach confirmed that exosome-transferred MMP14 participated in the regulation of cancer stemness of the recipient cells." (PMID 35223528, 2022).
cancer (continued). "There is no further data indicating that such a modification occurs for MMP-27 in cancer, but there are reports that, for instance, MMP-14 is phosphorylated in metastatic ovarian cancer compared to its wild-type." (PMID 36011038, 2022). "Many studies were focused on the proteolytic activity of MMP14 on the cell membrane where it cleaves and activates multiple proteins to promote cancer cell invasion." (PMID 35223528, 2022). "This study possibly implied that MMP-14 regulated CSCs to implicate in cancer invasion and chemoresistance." (PMID 35586209, 2022). "CA-IX has also been shown to enhance matrix metalloproteinase activity, in particular MMP-14 which is active at an acidic pH, resulting in stromal degradation that aids cancer migration into the periphery." (PMID 35840963, 2022). "Matrix metalloproteinase 14 (MMP-14) upregulation is often observed in invasive human cancers and correlates with the aggressiveness of human cancer cell lines." (PMID 35626707, 2022). "MMP-14 is among the key contributors to cancer invasion and promotes cancer development by activating proMMP-2 and degrading the ECM to promote cancer migration." (PMID 36776395, 2022). "MMP14 plays a crucial role in cancer migration and metastasis by ECM remodeling and cell motility, and MMP14 responses can be regulated by the scaffolding protein NEDD9 (neural precursor cell expressed developmentally downregulated 9) and TIMP2 levels." (PMID 36624735, 2022). "The podosome-related domains contain MMP14, which generates guidance tunnels within collagen gels in endothelial cells, and cancer cells use a similar mechanism as they move through the matrix." (PMID 36591235, 2022). "The positive staining of MMP14 was mostly observed in the cytoplasmic and cytomembrane of the carcinoma cells." (PMID 35957827, 2022). "Another example of the role of glycans in promoting cancer cell malignant behaviour is the matrix metalloproteinase MMP14, the main enzyme needed for cancer cell invasiveness." (PMID 34279699, 2021). "Some studies have reported that the collagen degradation by Mmp-14 is crucial for cancer cells to proliferate and invade in the ECM." (PMID 34207144, 2021). "MMP-14 knockdown by means of either RNA silencing or proteolytic shedding of the MMP-14 ectodomain diminishes cancer cell invasion." (PMID 35008569, 2021). "In this study, the prognosis of MMP14 in pan-cancer patients was analyzed, including OS, DSS, DFI, and PFI." (PMID 34604053, 2021). "At the same time, we further confirmed the expression of MMP14 in various cancers compared to normal tissues using the TIMER database." (PMID 34604053, 2021). "For example, MMP-14 can be downregulated by miR-181a-5p, thus inhibiting cancer cell migration and angiogenesis." (PMID 35008569, 2021). "MMP14 is highly expressed in numerous types of cancer, where it promotes angiogenesis, inflammation, cancer cell invasion, and metastasis." (PMID 34638754, 2021). "In contrast, in a collagen-rich environment, the invasion of cancer cells is increased by overexpression of MMP-14." (PMID 35008569, 2021). "This inhibition is incomplete emphasizing that additional mechanisms, such as MMP14 on cancer cells and αV integrin on infiltrating immune cells, including CD8+ and CD4+ TIL, and DC28,36, can activate latent TGF-β within the TME." (PMID 34471106, 2021). "The degradation of collagen type I alone involves cleavage of collagen fibers by the collagenolytic MMPs MMP-1, MMP-8, MMP13, and MMP14 (MT1-MMP) which can be expressed by cancer cells or stromal cells." (PMID 34956223, 2021). "Metastasis, migration and invasion associated cancer genes such as RanGAP1 (Ran-GTPase activating enzyme 1), Rho-like GTPase- Rac1, MMPs like MMP-9, MMP-14 and slug are found to be profoundly SUMOylated." (PMID 34715855, 2021). "Although MMP14 is an attractive target for cancer therapy, the development of drugs targeting MMP14 in vivo remains a difficult task." (PMID 34638754, 2021).
cancer (continued). "MMP14 is a membrane-type matrix metalloproteinase, which mediates processes such as extracellular matrix degradation and remodeling, cell invasion, and cancer metastasis." (PMID 33564303, 2021). "For example, MMP-14 empowers breast cancer TICs (tumor-initiating cells or cancer stem cells) to initiate tumors and activate motile programs under hypoxic nutrient-deprived conditions." (PMID 33946660, 2021). "MMP-14 also increases cancer invasiveness by cleaving the N-terminal heparin-binding domain of heparin-binding EGF-like growth factor (HB-EGF) to convert it into a heparin-independent growth factor." (PMID 35008569, 2021). "At present, there have been a few studies on MMP14, but this study is the first to consider MMP14 as a potential target in widespread cancer." (PMID 34604053, 2021). "The O-glycosylation pattern also determines the lifespan of MMP-14 and, thus, the invasiveness of cancer cells." (PMID 35008569, 2021). "Several previous studies have shown that IGFBP3, SOCS3, and MMP14 are related to radiosensitivity in certain types of cancers, which is consistent with our results that these three genes were highly expressed in radioresistant cells." (PMID 34638754, 2021). "MMP14 surface expression is tightly regulated and upregulation of MMP14 coincides with malignant cancer progression." (PMID 33672612, 2021). "While MMP-14 is physiologically expressed on different cell types, e.g., ECs and adipocytes, it is essential especially for cancer cells." (PMID 35008569, 2021). "MMP14 has been reported to be upregulated in some cancers and to promote invasion and metastasis of cancer cells." (PMID 34604053, 2021). "In cancer studies, miR-181a-5p inhibits cancer cell migration and angiogenesis via downregulation of matrix metalloproteinase-14 (MMP-14)." (PMID 33692799, 2021). "Among the MMPs, MMP-14 is the driving force behind extracellular matrix and tissue destruction during cancer invasion and metastasis." (PMID 35008569, 2021). "MMP-14 induces a mesenchymal phenotype in cancer and development, by cleaving BM components as well as E-cadherin." (PMID 35008569, 2021). "When we looked at extracellular proteases, matrix metallo-proteases in particular, we observed that Mmp-14, Mmp-19 and Mmp-8 were also up-regulated in SSMs in cancer." (PMID 34168645, 2021). "As the master MMP, MMP-14 is widely expressed on many cells and is particularly overexpressed on malignant cancer cells and correlates with poor prognosis." (PMID 35008569, 2021). "MMP14 is a member of the matrix metalloproteinase family and contributes to a key function in cancer metastasis, its expression is significantly correlated with poor OS." (PMID 34881236, 2021). "On the contrary, a blockade of cancer-linked soluble (MMP-1, -3, -7,-9) and membrane-bound (MMP-14) MMPs using a broadband MMP inhibitor partially reduced BM disruption events in highly invasive breast acini." (PMID 33921304, 2021). "The prognostic role of MMP-2, MMP-9, and MMP-14 in UM was recognized in several studies due to their crucial role in promoting cancer cell motility and angiogenesis, ultimately leading to the development of metastases." (PMID 34195299, 2021). "Cancer cells have been reported to express high levels of MMP-14 (known also as MT1-MMP) especially in the cell protrusions and extracellular vesicles (EVs)." (PMID 33917849, 2021). "MMP-14 expression varies depending on cancer type and is high in mesenchymal tumours, melanomas and brain tumours and also found in hepatic tumours and in carcinomas including breast cancer." (PMID 34344453, 2021). "MMP14, also called membrane type-1 matrix metalloproteinase (MT1-MMP), is a membrane-associated MMP that was originally discovered as a proMMP-2 activator, expressed on the surface of invasive cancer cells." (PMID 33805743, 2021).
cancer (continued). "Some recent studies showed that the inhibition of MMP14 improves the efficiency of chemotherapy and radiotherapy by reducing the migration and invasion of cancer, which is consistent with the results in our study." (PMID 34638754, 2021). "MMP14 is upregulated in many types of cancer, enhancing inflammation, angiogenesis, cancer cell invasion, and metastasis." (PMID 34572434, 2021). "Further results from this study extend the nature of the stromal subtypes: high MMP14-expression by both CAFs and cancer cells in FP fits with a dynamic stroma, undergoing active remodeling." (PMID 33672734, 2021). "Upon examination of VE-cadherin, ephrin A2, VEGFR2, laminin 5γ2, MMP1, MMP2, MMP9 and MMP14 by the human cancer cells, we made the surprise finding that of the genes investigated, VE-cadherin (CDH5) was the most highly expressed." (PMID 32246008, 2020). "For example, miR-181a-5p can downregulate MMP-14 and thereby inhibit the migration and angiogenesis of cancer cells." (PMID 33379400, 2020). "A recent study showed that Cy5-labeled M17, a DNA aptamer that specifically recognizes MMP14, is a promising molecular probe for imaging numerous types of MMP14-positive cancer cells." (PMID 32226524, 2020). "Recently, CAIX was found to be involved in cancer cell migration and MMP14-mediated invasion by supplying the protons needed for the catalytic activity of MMP14." (PMID 36046070, 2020). "Mesenchymal markers snail and MMP14 were upregulated in cancer cells maintained in 3D (P < 0.001), cadherin-11 was downregulated (P < 0.001) and HER2 increased (P < 0.05)." (PMID 32694700, 2020). "MMP-14 was originally found to contribute to cancer progression by activation of proMMP-2 and degradation of ECM to facilitate cancer metastasis." (PMID 32466129, 2020). "Our findings are consistent with the known role of MMP14, which is upregulated in several types of cancer and promote inflammation, angiogenesis, metastasis, and cancer cell invasion." (PMID 32974187, 2020). "It has recently been shown that β1 integrin-mediated Src-EGFR signaling regulates MMP-14 phosphorylation and thus the recycling of MMP-14 to sites of invadopodia formation during the invasion of cancer cells." (PMID 33379400, 2020). "MMP-14 is overexpressed in most human cancer, and the published studies have demonstrated that overexpression of MMP-14 in various cancers is associated with poor prognosis." (PMID 31956360, 2020). "This cell-surface processing sheds more light on the potential of various secreted MMP14 forms to be differentially regulated in normal and cancer cells by extracellular KLK14." (PMID 32575583, 2020). "Conversely, the overexpression of MMP-14 promotes the invasiveness of cancer cells in a collagen-rich environment." (PMID 33379400, 2020). "Other results establish the regulation of MMP-14 in cancers by miRNA-181a, and they further suggest strategies to elevate miRNA-181a to prevent cancer metastasis." (PMID 32403384, 2020). "Based on the results, MMP2, MMP9 and MMP14 expression levels were also reduced in cells treated with ampelopsin E. Production of MMPs correlates with the ability of cancer cells to perform EMT." (PMID 31323836, 2019). "Mechanistically, HIF2α, in concert with Sp1, can bind to the MMP14 promoter thereby enhancing its expression and the invasiveness of cancer cells." (PMID 31466240, 2019). "In cancer cell lines, the methylation status of both MMP14 and MMP2 promoters is inversely correlated to their gene expression and to the cell migratory ability." (PMID 31466240, 2019). "ECM stiffness has been linked to aggressiveness and EMT in various cancer cell types, and sensors of the mechanical properties of the ECM such as integrins are important players in MMP14-mediated cell invasion in 3D microenvironments." (PMID 31466240, 2019). "MMP14 is up-regulated in several types of cancer, promoting angiogenesis, inflammation, cancer cell invasion, and metastasis." (PMID 31466240, 2019).
cancer (continued). "Studies in cancer cell lines have long shown that the surface expressed MMP14 is predominantly enriched in the invadopodia (or podosomes)." (PMID 31439888, 2019). "In line with this concept, perturbing the key LE trafficking regulator Rab7 impairs MMP14-mediated activity for cancer cell migration and invasion." (PMID 31439888, 2019). "Combination activity of MMP2, MMP9 and MMP14 is crucial in initiating localized degradation of the gelatin by invadopodia during cancer metastasis." (PMID 31323836, 2019). "As mentioned, CLIC3 regulates the retrieval of LE-expressed MMP14 back to the degradative invadopodia in MDA-MB-231 cancer cells." (PMID 31439888, 2019). "During extravasation, cancer cells form membrane protrusions enriched by MMP14 and cortactin characteristic for invadopodia." (PMID 31167468, 2019). "Invadopodia facilitate the ECM degradation in a variety of cancers through the regulation of various MMPs, primarily MMP-14 (also known as MT1-MMP), MMP-2 and MMP-9." (PMID 30927923, 2019). "It has been reported that MMP14 functions as an oncogene and enhances the migration and adhesion induced by β-integrin in various cancer cells." (PMID 31810492, 2019). "Matrix metalloproteinase 14 (MMP-14) is a membrane-bound protein playing an important role in the stemness of aggressive cancers, including GBM 13-15, which makes it an appealing therapeutic target for GICs." (PMID 31723547, 2019). "Since the ectopic expression of the E7 oncoprotein from the highly pathogenic HPV 16 strain in carcinoma cell lines upregulates the expression of MMP9, MMP14 and MMP13, it is likely that this upregulation takes place through E2F." (PMID 31466240, 2019). "The MMP family represent an ideal group of targets to demonstrate our strategy because inhibiting MMPs is of clinical value, as both MMP9 and MMP14 are involved in cancer progression." (PMID 30174795, 2018). "Taken together, observations across different cancer types suggest that PROX1 negatively regulates MMP14 expression." (PMID 29934628, 2018). "We found a positive association between a high serum MMP-14 level and cancer stages III–IV (p = 0.029) and between a high serum MMP-14 level and distant metastasis (p = 0.022)." (PMID 30532247, 2018). "High serum MMP-14 was a statistically significant prognostic factor among patients with an intestinal type of cancer (hazard ratio [HR] 3.54; 95% CI 1.51–8.33; p = 0.004), but not among patients with a diffuse type." (PMID 30532247, 2018). "MMP14 localization to β1-integrin containing adhesion complexes has been demonstrated during cancer cell invasion process." (PMID 29712618, 2018). "CLIC3 promotes migration and invasion of cancer cells by facilitating the functions of MT1-MMP (MMP14)." (PMID 30165855, 2018). "Our work reveals that PROX1 regulates MMP14 expression in several cellular contexts, and thus represents an important modulator of normal and cancer cell behaviour." (PMID 29934628, 2018). "Here, we show that PROX1 suppresses the transcription of MMP14, a metalloprotease involved in angiogenesis and cancer invasion, by binding and suppressing the activity of MMP14 promoter." (PMID 29934628, 2018). "Taken together, demonstration that PROX1 negatively regulates MMP14 in normal tissues and in cancer supports the general nature of this signalling axis and its potential importance in physiological and pathological processes." (PMID 29934628, 2018). "Our results agree with MMP-14’s previously known role in promoting cancer cell invasion and the formation of metastases." (PMID 30532247, 2018). "Invadopodia formation requires MMP-14, a cell surface receptor that degrades collagen, and activates secreted MMPs, to promote cancer metastasis." (PMID 28938563, 2017). "Meanwhile, the roles of YY1 and miR-584-3p in regulating the MMP-14 expression warrant further investigation in other types of cancers." (PMID 28827574, 2017).